SNIP1 (Smad nuclear interacting protein 1)
Description:
Required for pre-mRNA splicing as component of the spliceosome. As a component of the minor spliceosome, involved in the splicing of U12-type introns in pre-mRNAs (Probable). Down-regulates NF-kappa-B signaling by competing with RELA for CREBBP/EP300 binding. Involved in the microRNA (miRNA) biogenesis. May be involved in cyclin-D1/CCND1 mRNA stability through the SNARP complex which associates with both the 3'end of the CCND1 gene and its mRNA.
Synonyms: PML1; NEDHCS; PMRED
Tractability: Small molecule: a structure with a bound ligand is known. PROTAC: UniProt records ubiquitination sites on it; ubiquitination databases record sites on it; its protein half-life has been measured.
Gene: Protein-coding gene on chromosome 1 (37,534,449 to 37,554,293, reverse strand). Ensembl gene ENSG00000163877.
Subcellular location: Nucleus
Subcellular location (Human Protein Atlas): Nucleoplasm; Cytosol
Pathways (Reactome):
Metabolism of RNA: mRNA Splicing - Major Pathway
Gene Ontology:
Molecular function: protein binding; RNA binding; mRNA binding; transcription regulator inhibitor activity
Biological process: miRNA processing; mRNA splicing, via spliceosome; mRNA stabilization; U2-type prespliceosome assembly; negative regulation of canonical NF-kappaB signal transduction; regulation of gene expression
Cellular component: nucleoplasm; nucleus; spliceosomal complex; U12-type catalytic step 2 spliceosome; U2-type catalytic step 1 spliceosome; U2-type precatalytic spliceosome; RES complex; U2 snRNP
Genetic constraint (gnomAD): Loss-of-function variants: 23 observed, 37.67 expected, observed/expected ratio (o/e) 0.61, 90% interval 0.44 to 0.87. The upper end of that interval is the gene's LOEUF score, 0.87, which puts it in group 3 of 6, group 1 being the genes least tolerant of losing a copy. Missense variants: 459 observed, 556.97 expected, observed/expected ratio (o/e) 0.82, 90% interval 0.76 to 0.89. Synonymous variants: 174 observed, 205.81 expected, observed/expected ratio (o/e) 0.85, 90% interval 0.75 to 0.96.
Homologues: Orthologues: chimpanzee SNIP1 (99% identical), macaque SNIP1 (97% identical), dog SNIP1 (89% identical), pig SNIP1 (89% identical), rabbit SNIP1 (88% identical), guinea pig SNIP1 (87% identical), rat Snip1 (85% identical), mouse Snip1 (83% identical), tropical clawed frog snip1 (54% identical), Caenorhabditis elegans pmlr-1 (39% identical), Drosophila melanogaster CG17168 (38% identical). Paralogues in human: SLC4A1AP (21% identical), PPP1R8 (11% identical).
Diseases named in the same sentence as SNIP1 in open-access papers:
SNIP1 is named in the same sentence as 56 diseases in open-access papers, as found by Europe PMC text mining. Sharing a sentence is not in itself a finding about the gene and the disease. The quoted sentences say what the papers report.
breast carcinoma (9 papers, 2017 to 2025). "Another prominent example is BCAR4 (breast cancer anti-estrogen resistance 4), which contributes to tumor metastasis by binding to SNIP1 (SMAD nuclear interacting protein 1) and PNUTS (a phosphatase)." (PMID 29416704, 2018). "Considering the critical role of the Hippo/YAP signaling pathway in KMT5A/SNIP1/MARK4-driven breast cancer progression and metastasis, the effects of verteporfin treatment combined with KMT5A-depletion on breast cancer metastasis were assessed." (PMID 35449131, 2022). "Also, its specificity for SNIP1-K301me1 was verified in MDA-MB-231 cells and a clinical breast cancer specimen." (PMID 35449131, 2022). "Further, the absence of SNIP1 K301 methylation significantly decreased growth, invasion, and lung metastasis of breast cancer cells, indicating that SNIP1 methylation regulates TNBC metastasis." (PMID 35449131, 2022). "Here, we identify that SNIP1 is a non-histone substrate of lysine methyltransferase KMT5A, which undergoes KMT5A-mediated mono-methylation to promote breast cancer cell growth, invasion and lung metastasis." (PMID 35449131, 2022).
epilepsy (4 papers, 2012 to 2023). A brain disorder characterized by episodes of abnormally increased neuronal discharge resulting in transient episodes of sensory or motor neurological dysfunction, or psychic dysfunction. "The E366G variant of SNIP1 has been linked to patients with psychomotor retardation, epilepsy, and craniofacial dysmorphism." (PMID 37553330, 2023). "Additionally, we examined publicly available data from Human Gene Mutation Database38 and Mastermind39 and identified a SNIP1 variant, R111C, that is significantly associated with epilepsy and skull dysplasia." (PMID 37553330, 2023). "Interestingly, a mutation in human SNIP1 (p.Glu366Gly) has been associated with epilepsy and skull dysplasia." (PMID 29969449, 2018). "Functional studies of BRAT1 and SNIP1 will expand our understanding of epilepsy and also deepen our knowledge of DNA damage repair and transcriptional regulation in cortical development and neuronal survival." (PMID 22279524, 2012). "Notably biallelic sequence variants within ROBO1 are associated with a neurodevelopmental disorder displaying many of the cardinal features seen in SNIP1-related disorder including neurodevelopmental delay, white matter abnormalities, epilepsy, autistic features, VSD and tetralogy of Fallot." (PMID 34570759, 2021).
osteosarcoma (4 papers, 2020 to 2023). A usually aggressive malignant bone-forming mesenchymal neoplasm, predominantly affecting adolescents and young adults. "SNIP1 depletion in a human osteosarcoma cell line U2OS increases sensitivity to cisplatin-induced apoptosis." (PMID 37553330, 2023). "Recently, SNIP1 was considered to be targeted by microRNA-335 and involved in osteosarcoma proliferation and metastasis." (PMID 33150075, 2020). "Over-expression of SNIP1 promoted cell invasion and migration in osteosarcoma cells." (PMID 33150075, 2020).
developmental delay (3 papers, 2018 to 2023). "The cardinal clinical features of SNIP1-related disorder include: hypotonia, global developmental delay, intellectual disability, seizures, a characteristic facial appearance and skull abnormalities." (PMID 34570759, 2021). "We propose that SNIP1, deleted in common with other reported individuals with similar deletions and developmental delays, is a strong candidate gene for the central nervous system pathology." (PMID 29726122, 2018). "The SNIP1 gene (OMIM 608241) has been associated with autosomal recessive cognitive impairment, developmental delay, seizures, structural brain abnormalities, and intellectual disability." (PMID 29726122, 2018).
triple-negative breast carcinoma (3 papers, 2022 to 2025). An invasive breast carcinoma which is negative for expression of estrogen receptor (ER), progesterone receptor (PR), and human epidermal growth factor receptor 2 (HER2). "SF3A2 and SNIP1 have been identified as crucial mediators implicated in the invasion of triple-negative breast cancer." (PMID 40134434, 2025).
cardiac hypertrophy (2 papers, 2016 to 2021). "In the present study, we utilized gain‐of‐function and loss‐of‐function approaches to investigate the role of SNIP1 in the pathogenesis of cardiac hypertrophy." (PMID 27912208, 2016). "Taken together, these data implied that SNIP1 deficiency accelerated cardiac hypertrophy and fibrosis under pressure overload." (PMID 27912208, 2016). "More importantly, IκBα overexpression rescued the deteriorating effects of SNIP1 deficiency on AB‐induced cardiac hypertrophy." (PMID 27912208, 2016). "Consistently, SNIP1 deficiency augmented pressure overload–induced cardiac hypertrophy as evidenced by HE and WGA staining." (PMID 27912208, 2016). "Hence, elucidation of the mechanisms underlying these characteristic phenomena related to SNIP1 will potentially further our understanding of cardiac hypertrophy and yield drugable targets for the intervention and prevention of cardiac hypertrophy." (PMID 27912208, 2016). "Together, these results indicated that the expression of SNIP1 was suppressed in cardiac hypertrophy." (PMID 27912208, 2016). "Here we examined the role of SNIP1 in pressure overload–induced cardiac hypertrophy and its mechanisms." (PMID 27912208, 2016). "Simultaneously, SNIP1 improved cardiac function and suppressed pathological cardiac hypertrophy and fibrosis." (PMID 27912208, 2016). "SNIP1 as a negative regulator of chronic pressure overload–induced cardiac hypertrophy prompted us to explore the mechanisms of SNIP1‐mediated antihypertrophic effects." (PMID 27912208, 2016). "In all, these evidences demonstrated that cardiac overexpressed SNIP1 attenuated AB‐driven cardiac hypertrophy." (PMID 27912208, 2016). "Taken together, we proposed that SNIP1 exerted cardioprotective effects in pathological cardiac hypertrophy in part through NF‐κB signaling." (PMID 27912208, 2016). "To explore the potential involvement of SNIP1 in cardiac hypertrophy, we first assessed the SNIP1 expression in hypertrophic hearts and cardiomyocytes." (PMID 27912208, 2016). "To verify the role of SNIP1 in chronic pressure overload–induced cardiac hypertrophy and fibrosis, we created 4 lines of cardiac‐specific SNIP1 transgenic (TG) mice." (PMID 27912208, 2016). "Together, our findings demonstrated that SNIP1 had protective effects in pressure overload–induced pathological cardiac hypertrophy via inhibition of nuclear factor‐κB signaling." (PMID 27912208, 2016). "Therefore, the results as shown in this study hint heretofore new direct evidence that the inhibitory effects of SNIP1 on cardiac hypertrophy were partly owing to suppression of NF‐κB signaling." (PMID 27912208, 2016). "Accordingly, SNIP1 deficiency significantly exacerbated aortic banding–induced cardiac hypertrophy, fibrosis, and contractile dysfunction, whereas cardiac‐specific overexpression of SNIP1 markedly recovered pressure overload–induced cardiac hypertrophy and fibrosis." (PMID 27912208, 2016). "Thus, further studies are needed to determine the therapeutic potential of SNIP1 for the treatment of pathological cardiac hypertrophy." (PMID 27912208, 2016). "Moreover, our data showed that overexpression of IκBαS32A/S36A obviously reversed the pro‐hypertrophic effects of SNIP1‐KO in AB‐induced cardiac hypertrophy, as evidenced by HW/BW, LW/BW, and HW/TL ratios, FS, ejection fraction, and LVDd values, and HE, WGA, and picrosirius red staining." (PMID 27912208, 2016). "To further explore the relationship of the NF‐κB p65 pathway and SNIP1 in AB‐induced cardiac hypertrophy, we crossed the cardiomyocyte‐restricted overexpression of phosphorylation‐resistant IκBα (IκBαS32A/S36A) mice with SNIP1‐KO mice to generate IκBα (IκBαS32A/S36A)‐TG/SNIP1‐KO mice." (PMID 27912208, 2016).
cardiac hypertrophy (continued). "Moreover, we identified that SNIP1 suppressed nuclear factor‐κB signaling during pathological cardiac hypertrophy, and inhibition of nuclear factor‐κB signaling by a cardiac‐specific conditional inhibitor of κBS32A/S36A transgene blocked these adverse effects of SNIP1 deficiency on hearts." (PMID 27912208, 2016). "Thus, comprehensive investigations are needed to determine whether SNIP1 would be a reliable therapeutic target for cardiac hypertrophy and remodeling." (PMID 27912208, 2016). "Remarkably, SNIP1 inhibition of this pathway reduced cardiac hypertrophy, while blocking the NF-kB pathway reduced the adverse effects of SNIP1 deficiency; these findings are notable as left ventricular noncompaction is also a feature seen in SNIP1-related disorder." (PMID 34570759, 2021). "However, the role of SNIP1 in cardiac hypertrophy remains unclear." (PMID 27912208, 2016).
lung carcinoma (2 papers, 2020 to 2021). "AFAP1-AS1 promoted lung cancer cells migration and invasion through interacting with Smad nuclear interacting protein 1 (named SNIP1), which inhibited ubiquitination and degradation of c-Myc protein." (PMID 34168109, 2021). "Ultimately, we found that AFAP1-AS1 enhanced the binding between Smad nuclear interacting protein 1 (SNIP1) and c-Myc proteins as a molecule guide in lung cancer." (PMID 34168109, 2021). "This study implies that AFAP1-AS1 mediates the binding of SNIP1 to c-Myc as a molecular guide and may have attractive potential for the therapy of lung cancer." (PMID 34168109, 2021). "And the knockdown of SNIP1 restrained the anchorage-independent growth of lung cancer cells." (PMID 33150075, 2020).
Neurodevelopmental delay (2 papers, 2018 to 2021). "It has been theorized that haploinsufficiency of the SNIP1 gene may lead to abnormal brain development and potentially neurodevelopmental delays." (PMID 29726122, 2018).
viral infection (2 papers, 2023 to 2024). "UBL5 (ubiquitin-like protein 5), SNIP1 (Smad Nuclear Interacting Protein 1), TWISTNB (RNA Polymerase I Subunit F) and MFAP1 (Microfibril Associated Protein 1) have not been reported in affecting viral infection before." (PMID 39715740, 2024).
Ataxia (1 paper, 2023). Ataxia refers to impaired coordination of voluntary muscle movement. "Heterozygous Snip1 KO (Snip1−/+) rescued NMF291−/− ataxia and significantly extended NMF291−/− life span, comparable to the extent of Snip1M/+." (PMID 37027487, 2023).
cervical cancer (1 paper, 2020). A primary or metastatic malignant neoplasm involving the cervix. "Further study is required to illustrate the underlying mechanism of miR-29a-3p/SNIP1 pathway in cervical cancer oncogenesis." (PMID 33150075, 2020). "In present study, we aimed to investigate the function of SNIP1 and identify novel miRNA-SNIP1 axis in the development of cervical cancer." (PMID 33150075, 2020). "In our analysis, the migration and proliferation of cervical cancer cells was significantly suppressed after siRNA-mediated silencing of SNIP1." (PMID 33150075, 2020). "In this research, we investigated the biological role of SNIP1 in the progression of cervical cancer." (PMID 33150075, 2020). "The newly identified miR-29a-3p/SNIP1 axis may provide new insights into the understanding of the progression of cervical cancer, and represent an effective treatment target for cervical cancer." (PMID 33150075, 2020). "The newly identified miR-29a-3p/SNIP1 axis could provide new insight into the development of cervical cancer." (PMID 33150075, 2020). "In conclusion, miR-29a-3p suppressed the migration and proliferation of cervical cancer cells by directly targeting SNIP1, and could also down-regulate the mRNA expression of SNIP1 downstream genes such as c-Myc, Cyclin D1 and HSP27." (PMID 33150075, 2020). "Therefore, miR-29a-3p may mediate the regulation of cell proliferation and migration in cervical cancer cells via downstream genes of SNIP1." (PMID 33150075, 2020). "However, the function of SNIP1 in cervical cancer development is poorly understood." (PMID 33150075, 2020). "However, the exact role of SNIP1 in the development of cervical cancer remains obscure." (PMID 33150075, 2020). "Hence, SNIP1 knockdown could reduce migration and proliferation in cervical cancer HeLa cells." (PMID 33150075, 2020). "Taken together, these results demonstrated that miR-29a-3p targeted SNIP1 via directly binding its 3′ UTR region and negatively regulated SNIP1 expression in cervical cancer." (PMID 33150075, 2020). "Furthermore, we predicted and demonstrated that miR-29a-3p inhibited the transcription and protein expression of SNIP1 by targeting 3′ UTR directly, and suppressed the proliferation and migration of cervical cancer cells." (PMID 33150075, 2020).
cervical squamous cell carcinoma (1 paper, 2020). A squamous cell carcinoma arising from the cervical epithelium. "Moreover, the expression relationship between miR-29a-3p and SNIP1 is negative correlation (P < 0.05) in cervical squamous cell carcinoma and endocervical adenocarcinoma (CESC) samples from starBase." (PMID 33150075, 2020).
colitis (1 paper, 2023). Inflammation of the colon. "Interestingly, one study discovered a considerable drop in SNIP1 expression in individuals with inflammatory bowel disease and intraepidermal carcinoma in a mouse model of colitis." (PMID 37620897, 2023).
colon cancer (1 paper, 2020). "DT inhibited protein expression of Skp2, Smad nuclear interacting protein 1 (Snip1), and Ras homolog gene family member A (RhoA) and induced apoptosis of HCT116 cells and HT-29 cells by reducing the secretion of CCL2 in macrophages and blocking the recruitment of colon cancer cells." (PMID 32265690, 2020).
dilated cardiomyopathy (1 paper, 2016). Cardiomyopathy which is characterized by dilation and contractile dysfunction of the left and right ventricles. "Here we report that SNIP1 was dramatically downregulated in human dilated cardiomyopathy hearts and AB‐induced murine hypertrophic hearts, as well as Ang II‐induced hypertrophic NRCMs." (PMID 27912208, 2016). "As compared with normal hearts, the protein levels of 2 prominent hypertrophic markers, ANP and β‐MHC, were highly upregulated, while expression of SNIP1 was significantly decreased in dilated cardiomyopathy hearts." (PMID 27912208, 2016).
heart failure (1 paper, 2016). Inability of the heart to pump blood at an adequate rate to meet tissue metabolic requirements. "Thus, SNIP1 upregulation may be a novel approach for the intervention and prevention of heart failure." (PMID 27912208, 2016). "Thus, SNIP1 may be a novel approach for the treatment of heart failure." (PMID 27912208, 2016).
leukemia (1 paper, 2025). A malignant (clonal) hematologic disorder, involving hematopoietic stem cells and characterized by the presence of primitive or atypical myeloid or lymphoid cells in the bone marrow and the blood. "This is supported by findings that Wilms’ tumor protein and Smad nuclear interacting protein 1 are indispensable for TET2 to suppress leukemia cell proliferation and regulate the cellular DNA damage response, respectively." (PMID 40459008, 2025).
macroglossia (1 paper, 2014). The presence of an excessively large tongue, which may be congenital or may develop as a result of a tumor or edema due to obstruction of lymphatic vessels, or it may occur in association with hyperpituitarism or acromegaly. "Normally, patients with SNIP1 mutations present bulbous nose, wide mouth and macroglossia." (PMID 25016475, 2014).
mesothelioma (1 paper, 2011). A usually malignant and aggressive neoplasm of the mesothelium which is often associated with exposure to asbestos. "We have analyzed a total of 4 genes: 2 genes that are up-regulated in H342-treated H2373 mesothelioma cells (Fos, JMJD7) and 2 genes that are down-regulated (SNIP1, SMAD6)." (PMID 21998702, 2011).
testicular cancer (1 paper, 2023). A primary or metastatic malignant neoplasm that affects the testis. "Furthermore, we performed single-gene GSEA of the dataset, which revealed an unknown relationship between SNIP1 and the TGF-β pathway in CRC; upon further investigation, we found that SNIP1 showed a negative association with the TGF-β pathway in testicular cancer." (PMID 37620897, 2023).